CD4 (CD4 molecule)
Diseases named in the same sentence as CD4 in open-access papers (continued):
Sharing a sentence is not in itself a finding about the gene and the disease.
chronic GVHD (continued). "The differentiation of the PSGL1loCD4+ T helpers in chronic GVHD recipients depends on the IL-6R-Stat3-BCL6 pathway, and Stat3 or BCL6 deficiency in donor CD4+ T cells prevented expansion of the PSGL1loCD4+ T cells in GVHD target tissues." (PMID 34539630, 2021). "In a lupus-like disease model resulting from a CD4 helper cell-driven chronic graft versus host disease, NPs induced CD4 and CD8 polyclonal Tregs that prevented the disease Here the antigen source was non-self MHC peptides." (PMID 34211471, 2021). "The autoreactive CD4+ T cells in chronic GVHD recipients are also derived from de novo-generated CD4+ T cells from GVHD-damaged thymus." (PMID 34539630, 2021). "In chronic graft-versus-host disease, autoreactive CD4+ TRMs recognize autoantigens presented by B cells to enhance production of IgG autoantibodies that augment skin damage." (PMID 34445713, 2021). "Chronic GVHD patients had markedly low percentages of Foxp3+CD4+ regulatory T (Treg) cells in the blood." (PMID 34539630, 2021). "Here we report studies of a patient with chronic GvHD (cGvHD) carrying persistent CD4+ T cell clonal expansion harboring somatic mTOR, NFKB2, and TLR2 mutations." (PMID 32382059, 2020). "Among UBMT patients, absolute cell number of naive CD4+ cell was significantly lower in patients with chronic GVHD." (PMID 32337009, 2020). "Bm12-induced chronic graft-versus-host disease (cGVHD) is initiated by injecting mice with MHC class II incompatible CD4+ T cells or unfractionated spleen cells." (PMID 32503684, 2020). "Chronic graft-versus-host disease (cGVHD) is mediated by specific CD4 and B cells, but the relative contribution of extrafollicular and germinal centre (GC) T-B interaction is unclear." (PMID 29042531, 2017). "Another recent study suggests a role of IL-26 in the pathogenesis of transplant-related obliterative bronchiolitisas IL-26+CD26+CD4+ T cells in part induces chronic GVHD of the lungs." (PMID 28819653, 2017). "Chronic GVHD recipients given CD4-Stat3+/+ TCD-BM and spleen cells completely lost lymphoid follicles and GCs." (PMID 29042531, 2017). "This “first-in-man-study” reported the adoptive transfer of ex vivo expanded CD4+CD25+CD127− Tregs in one patient with chronic GvHD and another with acute GvHD after HSCT with an HLA-identical sibling donor." (PMID 27909435, 2016). "CD4 T cells and B cells are essential for the induction of chronic graft-versus-host disease (cGVHD)." (PMID 26348529, 2015). "In chronic GVHD defects in central and peripheral tolerance mechanisms can lead to chronic stimulation of CD4+ T cells, which in turn activates macrophages, tissue fibroblasts and B cells." (PMID 26241482, 2015). "CD4 T cells, which are essential for the development of chronic GvHD in the B10.D2→Balb/c model, also probably played a role in the GvM effect." (PMID 25415267, 2014). "Treg number measured by CD4+CD25+FoxP3+ staining has been found to be decreased in patients with chronic GVHD." (PMID 23116248, 2012). "Taking together, the frequencies of uTh1 within total CD4+ T cells were significantly higher when acute and chronic GVHD developed." (PMID 22957070, 2012). "Most importantly, we observed that a decrease of both circulating CD161+CD4+ as well as CD161hiCD8+ T cells coincided with the occurrence of both acute and chronic GVHD." (PMID 23226545, 2012). "Our chronic GVHD mice showed a robust decrease in the percentage of CD4+CD25+FoxP3+ T cells, which was compromised by an expanded T cell population." (PMID 23116248, 2012). "Infusion of atRA/TGF-β-treated CD4+ cells resulted in the greater effects on suppressing symptoms and protecting the survival of chronic GVHD mice with typical lupus-like syndromes than did CD4+ cells treated with TGF-β alone." (PMID 21931768, 2011).
chronic GVHD (continued). "One of the interesting findings in the current study is that atRA/TGF-β-induced CD4+ regulatory T cells exhibit an enhanced suppressive T cell response in vitro and ameliorated lupus syndromes in a chronic GVHD animal model." (PMID 21931768, 2011). "As donor DBA/2 CD4+ T cells differentiate into Th2 cells in response to host BDF1 antigen presenting cells in chronic GVHD mice, we performed a DBA/2 anti-BDF1 MLR and examined the effect of HGF on the generation of Th1 and Th2." (PMID 16859527, 2006). "Chronic GVHD requires continuous donor CD4+ T cell activation through recognition of host MHC class II antigens." (PMID 16859527, 2006). "In D2→F1 chronic GVHD, D2 mice have a naturally occurring defect in initial IL-2 production that results in skewing of the initial donor CD4 T cell response away from a Th1 program, instead promoting the differentiation of T follicular helper (Tfh) cells and enhanced IgG antibody production." (PMID 38915570, 2024). "Therefore, PSGL1hi and PSGL1lo CD4+ Trm cells, macrophage, dendritic cells, B cells, and circulating IgG autoantibodies, all contribute to the pathogenesis of chronic GVHD, but CD4+ Trm cells play the essential role." (PMID 34539630, 2021). "In a mouse model of chronic GVHD, it was reported that ex vivo cultured MDSCs could modulate chronic GVHD presumably by preventing thymic tissue damages and reducing the percentages of CD4+ T cells that produced IL-17 (Th17 cells) and IL-4 (Th2 cells)." (PMID 32528476, 2020). "Besides, acute and chronic GVHD correlates with decreased levels of circulating CD161+CD4+ and CD161++CD8+ T-cells." (PMID 28626460, 2017). "Interestingly, occurrence of acute and chronic GVHD was significantly correlated with decreased levels of circulating CD161+CD4+ as well as CD161hiCD8+ T cells." (PMID 23226545, 2012). "Chronic graft-versus-host disease (GVHD), which is induced in (C57BL/6 × DBA/2) F1 (BDF1) mice by injection of DBA/2 spleen cells, is associated with the activation of donor CD4+ T cells that recognize host major histocompatibility complex (MHC) antigens and drive host B cell hyperactivity." (PMID 16859527, 2006). "It is possible that HGF may decrease the expression of MHC class II antigens on host B cells, which would suppress donor CD4+ T cell activation, and so reduce the Th2 response in chronic GVHD mice." (PMID 16859527, 2006). "However the proportion of CD4+ T cells generating cytokines, such as TNF-α, TGF-β, IL-21 and IL-13, which are critically involved in chronic GVHD, was significantly reduced in mLN from CpG-proB recipients, while only IL-13-expressing CD4+ T cells were diminished in pLN." (PMID 35479094, 2022). "Since autoimmune-like chronic GVHD can be induced in thymectomized and athymic recipients, the autoreactive CD4+ T cells in those recipients are most likely derived from the residual autoreactive CD4+ T cells in the graft that expanded during alloimmune responses." (PMID 34539630, 2021). "The autoreactive CD4+ T cells from both sources recognize donor antigen-MHC complex and host antigen-MHC complex, and they interact with autoreactive B cells to produce autoantibodies that further damaged the thymus and causes lymphopenia in chronic GVHD recipients." (PMID 34539630, 2021). "The interaction with PD-1 expressing CD8+ T-cells and PD-L1+ target tissues of GVHD resulted in T-cell exhaustion and apoptosis, thereby preventing acute GVHD but not chronic GVHD, which was associated with reconstitution of donor CD4+ T-cells beginning by day 21 post HSCT." (PMID 28613269, 2017). "Recovery of CD3+, CD4+, and CD8+ T-cell counts and TRECs was delayed in patients with moderate to severe chronic GVHD." (PMID 41012135, 2025). "We therefore examined the differentiation of IL-17A-producing CD4+ (Th17) and CD8+ (Tc17) T cells, which contribute to the development of fibrotic acute and chronic GVHD, especially in the skin." (PMID 38828727, 2024).
chronic GVHD (continued). "Low-dose IL-2 preferentially expanded CD4+ Treg cells by binding to high affinity IL-2Rα (CD25) and ameliorated clinical manifestation of chronic GVHD." (PMID 34539630, 2021). "PLGA NPs targeted to both CD4 and CD8 cells and encapsulated with IL-2 and TGF-β have been used to prevent a lupus-like syndrome (chronic graft versus host disease)." (PMID 34211471, 2021). "During chronic GVHD autoantibodies are produced due to the generation of autoimmune TFH and GC B cells in response to the donor CD4+ T cells." (PMID 31057553, 2019). "Given the important divergences in the pathogenesis of acute and chronic GVHD, we sought to investigate the impact of AZA in a well-established CD4-dependent murine model of scl-cGVHD." (PMID 27377819, 2016). "Imanguli and colleagues observed an upregulation of functional markers such as CD3+, CD4+, CD27+, ICOS+, and CD39+ in Tregs that traffic into tissue including skin and oral mucosa exerting a suppressive function in patients with chronic GvHD." (PMID 27909435, 2016). "Another possibility is that donor DBA/2 CD4+ T cells differentiate into Th2 in response to host MHC antigens and induce MHC class II expression on host B cells in chronic GVHD mice." (PMID 16859527, 2006). "Indeed, it is well known that chronic GVHD (and its treatment) has a profound impact on immunity after allo-HCT, affecting many cell subtypes such as B cells, CD4+ T cells, naive CD4+ T cells, TfH and CD8+ T cells." (PMID 34689821, 2021). "The discrepancy between mouse and human studies (and indeed, among human data) as to whether the CD4+ or CD4− iNKT population is best suited to reduce GVHD (and possible differences between acute and chronic GVHD) highlights the need for further study." (PMID 28824628, 2017). "CD4+ regulatory T-cell frequency was dramatically decreased in these patients comparing to patients without active chronic GVHD." (PMID 25674088, 2015). "Recent attention has focused on CD4+CD25+ Treg cells and their relationship to chronic GVHD." (PMID 23116248, 2012). "However, three doses of anti-CD4 monoclonal antibody on days 0, 14, and 28 prevented both acute and chronic GVHD, and subsequently recovered donor CD4+ T-cells did not cause chronic GVHD." (PMID 28613269, 2017). "The results showed an expansion of CD8 T cells, in contrast to CD4 T cells, but the expansion observed in co-cultures with MOPC315.BM cells was not different from co-cultures with Balb/cJ splenocytes, suggesting a close relationship between epitopes recognized in chronic GvHD and GvM processes." (PMID 25415267, 2014). "Importantly, we observed that percentages of Treg cells were high among CD4+ T cells in the spleen, liver, lung, and skin of healthy donor or GVHD-free recipients, but few Treg cells were found among CD4+ T cells in the same tissues from mice with chronic GVHD." (PMID 34539630, 2021). "Finally, lack of tolerogenic pDCs and Treg cells allow the cross-reactive autoreactive CD4+ Trm cells that recognize both donor antigen-MHC complex and host antigen-MHC complex to continuously interact with DCs, macrophages, and B cells to perpetuate chronic GVHD pathogenesis." (PMID 34539630, 2021). "In fact, the frequency of Treg, as marked by CD4+CD25+ expression, was lower in patients with chronic GVHD than in healthy controls or in patients post-transplant without chronic GVHD." (PMID 32793207, 2020).
chronic obstructive pulmonary disease (54 papers, 2004 to 2025). A chronic and progressive lung disorder characterized by the loss of elasticity of the bronchial tree and the air sacs, destruction of the air sacs wall, thickening of the bronchial wall, and mucous accumulation in the bronchial tree. "This hypothesis is consistent with some studies showing the presence of a SARS-CoV-2 reactive CD4 T cell subpopulation, manifesting cross reactivity with antigens of endemic coronaviruses, the causative agents of common cold." (PMID 33680349, 2021). "ILC2s isolated from the peripheral blood of patients experiencing acute exacerbation of chronic obstructive pulmonary disease (AECOPD) were co-cultured with CD4+T cells obtained from the peripheral blood of healthy individuals." (PMID 39897591, 2025). "Our findings demonstrated an increase in CD4 + T lymphocytes along with a decrease in CD8 + T lymphocytes among patients with chronic obstructive pulmonary disease (COPD)." (PMID 38605291, 2024). "IFN-γ+CD4+ cells (type 1 helper T cells, Th1) represent a critical component of the inflammatory environment in the lungs of chronic obstructive pulmonary disease (COPD)." (PMID 39555065, 2024). "CD4+FOXP3+ regulatory T cells (Treg) have been shown to be increased in the pulmonary lymphocyte follicles of chronic obstructive pulmonary disease (COPD) patients." (PMID 36139385, 2022). "In the murine lung epithelium, IL-17 overexpression led to inflammation with a chronic obstructive pulmonary disease-like phenotype involving CD4 cell recruitment, mucus hypersecretion, small airway fibrosis, and chemokine expression." (PMID 35163689, 2022). "The imbalance of CD4+Foxp3+ T cell subsets is reportedly involved in abnormal inflammatory immune responses in patients with chronic obstructive pulmonary disease (COPD)." (PMID 30842769, 2019). "Patient #4 suffered from severe chronic obstructive pulmonary disease and despite having 526 CD4+ cells/μl, his CD4/CD8 ratio was 0.3." (PMID 31636688, 2019). "The decline in lung function used to measure the progression of chronic obstructive pulmonary disease (COPD) has frequently been linked to the infiltration of lung tissues by polymorphonuclear leukocytes (PMNs), macrophages, CD4, CD8, and B cell lymphocytes." (PMID 28842670, 2017). "Likewise, MyD88-S is upregulated in stimulated CD4+ T cells from patients with Chronic Obstructive Pulmonary Disease (COPD)." (PMID 36531997, 2022). "In patients with chronic obstructive pulmonary disease (COPD), the microbiome analysis revealed a reduction in microbial diversity associated with remodelling of the alveolar and bronchiolar tissue, the infiltration of CD4+ T-cells, and emphysematous destruction." (PMID 35763685, 2022). "It is known that increased presence of CD4+ and CD8+ T lymphocytes in the lung is associated with Chronic Obstructive Pulmonary Disease (COPD), as it is believed that CD8+ T lymphocytes cause modifications in the elastic fibers and musculature of the bronchi." (PMID 39967674, 2025). "The medical history of this patient revealed that the patient had a chronic obstructive pulmonary disease (COPD) and was on antiretroviral therapy with current CD4 counts of 150 cells/μL and plasma HIV RNA of 22 copies/ml." (PMID 32357915, 2020). "Therefore, to avoid cardiac arrhythmia via down-regulation of the fraction of CD4+CD28null cells, a safe and feasible pre-optative stain-therapy could represent a potential therapeutic agent." (PMID 29941960, 2018). "IFN-γ-producing CD4+ T (Th1) cells and IL-17-producing CD4+ T (Th17) cells play a critical role in the pathogenesis of chronic obstructive pulmonary disease (COPD)." (PMID 27994590, 2016). "CD4+ T cells in the lung are involved in the pathogenesis of chronic obstructive pulmonary disease (COPD), although CD4+ T cell subsets and the direct effect of smoking on these cells, especially the expression of MRs, have not been comprehensively examined." (PMID 25375131, 2014).
chronic obstructive pulmonary disease (continued). "Lung CD4+ T cells accumulate as chronic obstructive pulmonary disease (COPD) progresses, but their role in pathogenesis remains controversial." (PMID 24805101, 2014). "Several studies have reported a reduction in the concentration of CD4+ and CD8+ T cells in peripheral blood during acute exacerbations of chronic obstructive pulmonary disease." (PMID 38031059, 2023). "Our previous studies defined that in patients with acute exacerbation of chronic obstructive pulmonary disease (AECOPD), the metabolic insufficiency of exhausted CD4+ or CD8+ T cells occurred and the targeting glycolysis of T cells restored immune functions." (PMID 34841705, 2021). "He had a past medical history of severe chronic obstructive pulmonary disease (COPD), treated with home oxygen over the last year, history of AIDS for 17 years, receiving antiretroviral medications, (last documented HIV RNA load of 14,070 copies/mm3 and a CD4 count of 285/mm3)." (PMID 24511405, 2014). "Vaccine immunogenicity may be reduced in patients with chronic obstructive pulmonary disease (COPD), HIV infection (at CD4 counts <500/μL), and cancer." (PMID 40936925, 2025).